ALCAM (activated leukocyte cell adhesion molecule)
Diseases named in the same sentence as ALCAM in open-access papers (continued):
Sharing a sentence is not in itself a finding about the gene and the disease.
tumor (continued). "In a cohort study of recurrent hepatocelluar carcinoma, the ALCAM-positive group was found to take a longer time to recurrence than those with ALCAM-negative tumours." (PMID 34680335, 2021). "In a cohort of 175 pleural mesotheliomas, 25% of the tumours showed positive staining of ALCAM, mostly membraneous." (PMID 34680335, 2021). "In preclinical studies, blocking VLA-4 or ALCAM on tumour cells (via incubation with neutralizing antibodies) resulted in a significant decrease in the number and volume of BM in comparison to the unblocked cells." (PMID 34504791, 2021). "ALCAM expressed on mesenchymal stem cells has also been demonstrated to assist the cells to migrate toward tumours, such as glioma in the brain, a tumour tropic movement." (PMID 34680335, 2021). "In a rare tumour type, namely giant cell bone tumours, ALCAM-positive tumour cells were more resistant to chemotherapeutic agents, including cisplatin, and also more resistant to radiotherapy." (PMID 34680335, 2021). "Zarghami and colleagues have conjugated iron oxide microparticles to anti-ALCAM (mouse) antibody and used the conjugate as an imaging tool to detect brain metastasis from various tumour types." (PMID 34680335, 2021). "Following surgery, a dramatic reduction in the soluble form of ALCAM in the serum was observed, overall arguing a possible role of serum ALCAM as a possible surrogate marker in response to surgery or the degree of removal of tumours by surgery." (PMID 34680335, 2021). "Brain metastases in selenoglycoprotein fed mice had markedly reduced brain metastasis and tumour intra- and extravasation in brain vasculatures, which appears to be a result of reduction in ALCAM and PECAM1 in the mice." (PMID 34680335, 2021). "This rise likely assists the endothelial-tumour interactions for seeding and settling of cancer cells in the brain and is supported by additional evidence that anti-ALCAM antibodies significantly inhibited the number of metastatic tumours in the brain." (PMID 34680335, 2021). "Both the membranous staining and messager level of ALCAM was seen in tumours with lymphatic invasion." (PMID 34680335, 2021). "In this study, we find that the tumor marker CD166/ALCAM (Activated Leukocyte Cell Adhesion Molecule) is a clathrin-independent cargo." (PMID 32193381, 2020). "In the seven WNT molecular subgroup cases, the tumor cells of the whole section were diffusely stained for ALCAM." (PMID 33270750, 2020). "In the current study, we performed Immunohistochemical evaluation of ALCAM in representative tumor areas." (PMID 33270750, 2020). "Knockdown of either Wnt5a or ALCAM inhibited tumour cell migration, confirming the role of the Wnt5a/ALCAM axis in the migratory phenotype of ER-positive BC." (PMID 33080952, 2020). "ALCAM appeared to be involved as a positive regulator of proliferation and migration of MB tumor cells in vitro." (PMID 33270750, 2020). "Nevertheless, ALCAM-negativity at the invasive front of the tumor has been reported as a marker of myometrial invasion in tissue of endometrioid endometrial cancer." (PMID 33270750, 2020). "These cells expressed both primary melanocytic tumor markers (MLANA, ALCAM) and tumor-promoting M2 macrophage markers (CD206, CD208)." (PMID 32182935, 2020). "The results showed delayed in vivo growth of tumor cells constitutively expressing high CD166/ALCAM surface levels in transgenic shCD6lckEμTg mice compared with WT controls." (PMID 33287301, 2020). "We have demonstrated that the tumor marker ALCAM/CD166 is a CIE cargo that is internalized in an endoA3-dependent manner." (PMID 32193381, 2020). "Given its high expression in multiple tumor types, CD166, also known as activated leukocyte cell adhesion molecule (ALCAM), appeared to be an attractive target for ADC approaches 20-22." (PMID 32483421, 2020). "Most of the ALCAM-positive tumor cells stained predominantly in the cytoplasm, but a few of them showed some staining in the cell membrane." (PMID 33270750, 2020).
tumor (continued). "Mannosidase-mediated N-glycosylation has a strong impact on tumour cell aggregation and affects the prognostic impact of the adhesion molecule ALCAM." (PMID 31659304, 2019). "Surprisingly, the opposite result was found in tumours with low-MAN1A1 protein levels (probably leading to higher amounts of high-mannose N-glycans), where high ALCAM levels were rather associated with a better prognosis." (PMID 31659304, 2019). "In multivariate Cox regression analysis including clinical stage and residual tumour after surgery, ALCAM lost its prognostic significance in groups with high or low-MAN1A1 expression." (PMID 31659304, 2019). "The overarching goal of this study was to determine how ALCAM shedding regulates tumor cell biology." (PMID 29453336, 2018). "In this manuscript, we examined the functional and biochemical differences between ALCAM-Iso1 and ALCAM-Iso2 in the context of tumor progression." (PMID 29453336, 2018). "In those, MMP-9 increased concomitant with a decrease in ALCAM from the superficial area to the invasive front of the tumor." (PMID 29682175, 2018). "ALCAM presented a significant positive correlation with the major adhesion complex at the superficial area of the tumor." (PMID 29682175, 2018). "At the superficial area, ALCAM expression was unrelated to the clinical parameters of myometrial invasion, tumor grade, and tumor progression." (PMID 29682175, 2018). "The uterine aspirate is a bodyfluid that is collected from inside of the uterine cavity, and is mainly formed by the secretion of the tumor cells and other cells from the endometrium, enabling the detection of cleaved ALCAM produced by the tumor." (PMID 29682175, 2018). "In this manuscript, we describe how alternative splicing of ALCAM controls the functional contribution of ALCAM to tumor biology." (PMID 29453336, 2018). "As our previous results indicated a different behavior of ALCAM regarding tumor differentiation, analyses were performed in the entire population, and in the well-differentiated (GI) and poorly-differentiated (GII-III) subcohorts." (PMID 29682175, 2018). "In this regard, promoter hypermethylation of the ALCAM gene is thought to downregulate transcription in tumor tissues." (PMID 29315254, 2018). "We investigated the effect of ALCAM-Iso1 and ALCAM-Iso2 expression on metastasis, tumor cell aggregation, and ALCAM homotypic interactions." (PMID 29453336, 2018). "In this tumor area, ALCAM significantly decreased along tumor stages and in tumors with myometrial invasion >50%." (PMID 29682175, 2018). "The requirement for both the loss of exon 13 and the gain of metalloprotease activity suggests that ALCAM shedding and concomitant regulation of tumor cell adhesion is a locally tunable process." (PMID 29453336, 2018). "Taking into account that myometrial invasion is highly associated with poor prognosis and to a limited therapeutic response, our research opens an avenue for the use of ALCAM-recovery as a therapeutic approach to control tumor invasion." (PMID 29682175, 2018). "Next, Kaplan-Meier curves for overall survival were plotted for tumor stage, urine ALCAM and serum ALCAM." (PMID 27894096, 2017). "We found that the expression level of ALCAM was negatively correlated with microvascular invasion and tumor size." (PMID 29375378, 2017). "Tumor stage, positive lymph-node status, age and urine ALCAM had relatively high correlation with survival time compared to urine hemoglobin and serum ALCAM." (PMID 27894096, 2017). "To better understand the potential role of ALCAM in miR-483-5p-mediated tumor invasion and metastasis, we performed gain-of-function and loss-of-function analyses." (PMID 29375378, 2017). "Since both serum and urine ALCAM concentrations were elevated in BCa, we set out to determine if either correlated with tumor stage and/or patient outcome using the VUMC cohort (n = 120)." (PMID 27894096, 2017).
tumor (continued). "ALCAM-mediated adhesion is disrupted when its ectodomain is shed by ADAM17 from the surface of tumor cells during malignant transformation." (PMID 27894096, 2017). "Urine ALCAM still had similar prediction strength as tumor stage based on adjusted partial likelihood ratio Chi-square statistics." (PMID 27894096, 2017). "Of note, the multivariable prediction strength of urine ALCAM nearly matches that of tumor stage based on adjusted partial likelihood ratio Chi-square statistics." (PMID 27894096, 2017). "In contrast, urine ALCAM correlates with tumor stage and is a significant independent predictor of 3-year overall survival for patients after cystectomy." (PMID 27894096, 2017). "At both 48 h and 3 weeks post tumor cell infusion, there was a significant interaction between diet and tumor cell infusion on ALCAM mRNA levels." (PMID 26706037, 2016). "ALCAM mRNA levels showed significant upregulation at a 48-h time point in the tumor cell infused mice for all dietary group except the SeGP65 fed group, where the differences were not significant." (PMID 26706037, 2016). "In tumor pathology, ALCAM expression varies from strong (colon, gastric, and pancreatic cancer) to weak (breast cancer), depending on cellular type and on the modified microenvironment." (PMID 26339605, 2015). "In patients without regional lymph nodes metastases (N-) a statistically significant correlation was observed between increased ALCAM expression in the primary tumor and shorter CSOS and DFS (P = 0.006 and P = 0.001, respectively)." (PMID 26134500, 2015). "No other statistically significant correlations were identified between ALCAM expression parameters and other clinical features such as tumor location, age or sex." (PMID 26134500, 2015). "Earlier studies have shown that ALCAM is a valuable cancer stem cell marker in various cancer types and plays a role in tumor progression, e.g., in breast cancer." (PMID 26703751, 2015). "This cytoplasmic specificity discriminates the advanced stages from the early ones, which designates ALCAM as a useful marker in the attempt to prove the effect of destruction of the intercellular binding, in tumor versus normal context." (PMID 26339605, 2015). "The Rac-specific guanine nucleotide exchange factor Tiam1 which is one important regulator of Rho GTPase functions in tumor cells is also functionally involved in ALCAM-dependent cell adhesion and reduces cell migration in metastatic melanoma cells." (PMID 26703751, 2015). "This statement opens a series of new perspectives for the reappraisal of the significance of ALCAM expression as indicator for tumor progression ability." (PMID 26339605, 2015). "This process is driven in part by proteolytic cleavage of membrane bound ALCAM by ADAM/TACE and its subsequent loss from intercellular tumor junctions." (PMID 25255861, 2014). "Multivariate analysis demonstrated that ethnicity contribute significantly to ALCAM expression after accounting for basal-like subtype, age, histological grade, tumor size, and lymph node status." (PMID 25255861, 2014). "We developed a Immunoreactive Score (IRS) by combining both intensity of IHC and percentage of ALCAM-positive tumor cells." (PMID 25255861, 2014). "Immunohistochemical staining was used to semi-quantitatively score ALCAM expression in tumor and adjacent non-tumor breast tissues." (PMID 25255861, 2014). "ALCAM is thought to contribute to events that influence the transition of homotypic behavior in tumor masses to heterotypic interactions with surrounding cell types." (PMID 25255861, 2014). "Patients, whose tumor samples showed ALCAM overexpression receiving a cytotoxic therapy like radiotherapy or chemoradiation, however, had a favourable prognosis compared to those patients, whose cancers showed no or minimal ALCAM staining." (PMID 22475274, 2012).
tumor (continued). "The sensitivity (58.6%) and specificity (73.9%) of s-ALCAM was clearly inferior to the tumor marker most frequently used for PAC, CA19-9, (sensitivity of 58% to 87%, specificity of 93%)." (PMID 22745698, 2012). "Evaluation of ALCAM expression in a collection of 6 tumor-derived cell lines was used as an initial platform." (PMID 23024593, 2012). "We found this phenotype to be particularly interesting in light of dozens of reports identifying ALCAM as a potential regulator of tumor cell behavior." (PMID 22745734, 2012). "Median preoperative s-ALCAM concentration in sera from tumor patients was 27.6 ng/ml (range 17.5-55.1 ng/ml, mean 28.9 ng/ml), serum levels did not correlate with intratumoral ALCAM expression." (PMID 22475274, 2012). "We also correlated s-ALCAM levels to clinicopathological factors as described for ALCAM expression in tumor tissue." (PMID 22475274, 2012). "MCAM, ALCAM, NCAM, and L1CAM have all been implicated in the formation of large cell aggregates and have been shown to increase the metastatic capability of tumour cells." (PMID 22272201, 2012). "Reports from the literature thus present a paradox regarding ALCAM’s relationship to tumor cell motility and invasiveness." (PMID 22745734, 2012). "ALCAM expression patterns varied from focal staining in specific tumor areas to ALCAM reactivity in all tumor cells, with both membraneous and cytoplasmic staining in varying proportions." (PMID 22475274, 2012). "Depending on the tumor cell type, ALCAM expression has been reported to be both positively and negatively correlated with cancer progression and metastasis in the literature." (PMID 22745734, 2012). "The ALCAM staining pattern appeared to be stronger in tumor samples, especially in MTCs, and revealed several discrete bands ranging from 120 to 100 kDa, probably due to a different level of glycosylation." (PMID 21364949, 2011). "Using genetic and antibody blocking assays we demonstrate that ALCAM enhances homotypic adhesion of tumor cells perfusing through the pulmonary vasculature." (PMID 20929568, 2010). "ALCAM expression increased by 3-fold the number of MDA-MB-435 tumor cell clusters, while anti-ALCAM antibody reduced this number significantly." (PMID 20929568, 2010). "Restoration of high-level ALCAM expression using an ALCAM cDNA increased clustering of MDA-MB-435 tumor cells perfused through the pulmonary vasculature of ventilated rat lungs." (PMID 20929568, 2010). "We studied ALCAM expression in 20 tumor cell lines by real-time PCR, western blot and immunochemistry." (PMID 20929568, 2010). "The isolated ventilated perfused rat lung system has previously been used to investigate the fate of circulating tumor cells, and was employed here to test the influence ALCAM has on these cells." (PMID 20929568, 2010). "The data reported here suggests that ALCAM is likely to slow down this process, by promoting homotypic tumor cell adhesion." (PMID 20929568, 2010). "Pre-treating ALCAM-positive MDA-MB-435 cells with anti-ALCAM antibodies prior to perfusion significantly reduced the number of tumor cells in the rat lung." (PMID 20929568, 2010). "Sequencing of bisulfite-modified DNA revealed that virtually all CpG islands in the proximal ALCAM promoter were methylated in MDA-MB-435 tumor cells, with percentage methylation ranging from 15% to 60%." (PMID 20929568, 2010). "Additional mechanistic studies are needed to clearly define the relationship between ALCAM level and the metastatic phenotypes of tumor cells." (PMID 20929568, 2010). "ALCAM was generally expressed at cell-cell contacts of confluent tumor cell cultures although cytoplasmic localization was also detected." (PMID 20929568, 2010). "This idea is pertinent to the level of ALCAM expression and the metastatic phenotypes of the two tumor cells lines we used in our lung perfusion experiments." (PMID 20929568, 2010).
tumor (continued). "In this study, we examined the impact of ALCAM on the adhesive behavior of tumor cells in the pulmonary vasculature using the isolated rat lung system." (PMID 20929568, 2010). "ALCAM's role in adhesion of tumor cells to the vascular wall was studied in isolated perfused lungs." (PMID 20929568, 2010). "Experiments using two function blocking ALCAM antibodies, and genetically-modified MDA-MB-435 clones ectopically expressing ALCAM, revealed that ALCAM promotes homotypic tumor cell adhesion demonstrated by clusters of tumor cells in the pulmonary vasculature." (PMID 20929568, 2010). "In some tumour types membranous expression is associated with worse prognosis, whereas in other tumour types cytoplasmic localisation of ALCAM is an adverse prognostic parameter." (PMID 19603023, 2009). "Disruption of the ALCAM-mediated adhesiveness by proteolytic sheddases such as ADAM17 has been suggested to have a relevant impact on tumour invasion." (PMID 19603023, 2009). "They postulated that the disruption of the ALCAM-mediated adhesiveness is a relevant step, which increased the invasiveness of tumour cells." (PMID 19603023, 2009). "For example, immunoliposomes coupled with anti-ALCAM single-chain antibody fragments (scFv) have been used to deliver anti-tumor agents to prostate cancer cells, opening avenues for the future design of functionalized nanotherapeutics targeting EndoA-mediated endocytic axes." (PMID 40986063, 2025). "Regarding ALCAM, all tumor cells were positive for the molecule with variable expression levels." (PMID 40391211, 2025). "Cells treated with recombinant Wnt5a demonstrated a decrease in both ALCAM and vinculin, supporting the hypothesis that the interaction of these two proteins is affected by Wnt5a in the tumor microenvironment." (PMID 41301074, 2025). "Notably, we identified SLC26A3high tumor cells expressing ALCAM in close proximity to CD6+Tregs, suggesting potential involvement of ALCAM>>CD6 signaling in Treg recruitment." (PMID 40066698, 2025). "We then validated that ALCAM is expressed on macrophages in human and mouse tumor tissues." (PMID 38956900, 2024). "As a highly differentiated M2-like TAMs subset, bM2-like TAMs may play an anti-tumor role by activating T cells via ALCAM/CD6 interactions, as well as by promoting α-SMA+ myofibroblasts production via TGF-β secretion." (PMID 39507421, 2024). "Moreover, they reported that ALCAM in vitro appeared to be involved as a positive regulator of the proliferation and migration of MB tumor cells, whereas ALCAM silencing in vivo enhanced tumor cell invasion at the dissemination sites." (PMID 38730706, 2024). "Specifically, we studied whether ALCAM acts as both a ‘seed’ receptor in these tumour cells and a ‘soil’ receptor in peritoneal mesothelial cells during cancer metastasis." (PMID 36614319, 2023). "Though in vivo efficacy and toxicity studies are still to come, the dependence on surface CD166/ALCAM dosage may help minimise on-target off-tumour toxicity." (PMID 38139340, 2023). "Overexpression of endogenous CD6 ligands (i.e., CD166/ALCAM, CD318/CDCP1, and CD44) is associated with tumour events, so the use of CD6-based CARs may broaden the spectrum of treatable tumours." (PMID 38139340, 2023). "Moreover, mice injected with ALCAM-knockdown cells resulted in fewer tumor dissemination to the brain with a significant reduction in both the size and number of BM." (PMID 37190188, 2023). "Whether shCD6 would interfere with the function of other CD166/ALCAM-expressing immunosuppressive cells from the tumour microenvironment (e.g., mesenchymal stromal cells) should be further addressed." (PMID 38139340, 2023). "We next examine if the SRC kinase may contribute to the tumour-mesothelial interaction mediated by ALCAM seen here." (PMID 36614319, 2023).